HACE1 (HECT domain and ankyrin repeat containing E3 ubiquitin protein ligase 1)
Diseases named in the same sentence as HACE1 in open-access papers (continued):
Sharing a sentence is not in itself a finding about the gene and the disease.
tumor (40 papers, 2009 to 2025). "HACE1, known as a renowned tumor suppressor gene, is located within the tumor suppressor region on chromosome 6q21, encoding a protein with a relative molecular mass of approximately 103 kDa." (PMID 40948788, 2025). "Studies have shown that the tumor suppressor function of HACE1 is closely linked to its E3 ubiquitin ligase activity." (PMID 40948788, 2025). "Increased methylation of CpG177 is associated with decreased HACE1 expression in tumor tissue compared to normal tissue." (PMID 40948788, 2025). "The loss of HACE1 leads to an increase of RAC1 activity that contributes to tumour growth, cell migration and cancer progression." (PMID 40396280, 2024). "The results showed that ectopic expression of HACE1 caused a lower radiosensitivity of tumor cells than the control, as reflected by cell survival." (PMID 34815381, 2021). "HACE1 loss promotes tumor growth, invasion, and metastasis; therefore, this E3 ubiquitin ligase functions as a tumor suppressor." (PMID 33825941, 2021). "HECT domain and ankyrin repeat containing E3 ubiquitin protein ligase 1 (HACE1) is an E3 ubiquitin ligase located on chromosome 6q21 that plays a crucial role in tumor biology and is closely associated with survival outcomes." (PMID 34627241, 2021). "Further studies will focus on the link of the spontaneous mutation of HACE1 with inflammation or tumor development, which will be intriguing." (PMID 27213432, 2016). "The pharmaceutical interference of Rac function abrogates the effects of HACE1 loss both in vitro and in vivo, resulting in marked reduction in tumor burden." (PMID 25659579, 2015). "Although we cannot at present exclude a predisposition for late-onset tumours in the HACE1-deficient individuals, it therefore appears possible that the previously reported heterozygous mutations in cancer patients were incidental findings." (PMID 26424145, 2015). "HACE1 is believed to regulate the activity of a number of small GTPases, and previous genetic studies have mostly implicated it as a tumour suppressor." (PMID 26424145, 2015). "This avoidance of the production and accumulation of oxidative damage may be the underlying mechanism of the HACE1-OPTN-p62 axis inhibiting tumor growth and tumorigenicity." (PMID 40948788, 2025). "HACE1 was originally identified as a tumor suppressor based on loss of expression in WT." (PMID 33603169, 2021). "It has previously been suggested that HACE1’s tumor suppressor activity may be linked to cellular stress responses." (PMID 33603169, 2021). "While HACE1 has multiple targets, it has been shown that loss of HACE1 increases Rac1 activity, which induces reactive oxygen species generation and cell migration that likely contribute to Rac-mediated tumor progression." (PMID 30544910, 2018). "As a well-known tumor suppressor, HACE1 can inhibit the growth, invasion, and metastasis of multiple cancer types." (PMID 40948788, 2025). "HECT domain and ankyrin repeat-containing E3 ubiquitin-protein ligase 1 (HACE1) is a well-known tumor suppressor and is essential for embryonic development." (PMID 40948788, 2025). "As an autophagy adapter protein, HACE1 prevents cellular oxidative damage and tumor progression by activating autophagy to remove toxic proteins and damaged organelles through the ubiquitination of the selective autophagy receptors p62 and OPTN." (PMID 40948788, 2025). "HACE1 blocks the generation of ROS by Rac1-dependent NADPH oxidases, thereby alleviating the initiation and progression of tumor cells caused by DNA oxidative damage and cyclin D1-driven hyperproliferation." (PMID 40948788, 2025). "Enhancing HACE1 expression by regulating methylation leads to extensive research on its regulatory mechanism and its tumor-suppressive effect." (PMID 40948788, 2025). "As an important factor in the modulation of cellular stability and survival, HACE1 plays a significant role in regulating oxidative stress, autophagy, and tumor suppression." (PMID 40948788, 2025).
tumor (continued). "Taken together, these studies support the notion that HACE1 exerts a tumor suppressor function by regulating cyclin D1." (PMID 40948788, 2025). "In this review, we first introduce the protein structure and function of HACE1 and then provide a systematic mechanism analysis of its redox signaling pathway, autophagy pathway, and tumor suppressor pathways." (PMID 40948788, 2025). "Taken together, HACE1 regulates cellular oxidative stress in a Rac1-dependent manner and is essential in organ development and tumor suppression." (PMID 40948788, 2025). "The HACE1 E3 ubiquitin ligase is a tumour suppressor that ubiquinates active RAC1 at the Lys147 residue, leading to its degradation." (PMID 40396280, 2024). "Collectively, these findings corroborate HACE1's role as a tumor suppressor within the realm of ESCA." (PMID 38706891, 2024). "The E3 ubiquitin ligase HECT domain and ankyrin repeat containing E3 ubiquitin protein ligase 1 (HACE1) is a potent tumor suppressor that controls cellular proliferation and ubiquitylates the small GTPase RAC1 to target it for proteasomal degradation." (PMID 38169395, 2024). "As previously reported, HACE1 functions as a tumor suppressor by ubiquitinating OPTN and activating selective autophagy." (PMID 38660717, 2024). "A previous study reported that the ubiquitination of the autophagy receptor OPTN (optineurin) by HACE1 activates selective autophagy for tumor suppression." (PMID 38660717, 2024). "The model constructed with HACE1-silenced TE-1 cells exhibited heightened tumor volume and mass post-HACE1 inhibition." (PMID 38706891, 2024). "The effects of HACE1 on ESCA cells through RAC1 were elucidated by applying the RAC1 inhibitor EHop-016 in a tumor-bearing nude mouse model." (PMID 38706891, 2024). "Employing Eca-109 cells overexpressing HACE1, the resulting model mirrored cell experiment outcomes, with tumor volume and mass significantly suppressed upon HACE1 elevation." (PMID 38706891, 2024). "For instance, E3 ubiquitin ligase HACE1 downregulates Rac1 activity and functions as a suppressor in Rac1-mediated tumor progression." (PMID 38809020, 2024). "HACE1 has attracted much attention in recent years because of its involvement in the development of human malignancies, in which it acts as a tumor suppressor." (PMID 36825281, 2023). "This commentary extends the discussion about the molecular function of HACE1 beyond its role in tumour biology and highlights the importance of establishing crosstalks between rare diseases and more common disorders." (PMID 35678127, 2022). "HACE1 is an E3 ligase, which resides in cytoplasm and functions as a tumour suppressor in different cancers." (PMID 35343092, 2022). "To probe the pathophysiological significance, we investigated the relative levels of HACE1 and HIF1α protein in WT cases compared with patient-matched normal kidney adjacent to tumor tissues." (PMID 33603169, 2021). "HACE1, an E3 ubiquitin-protein ligase, is frequently inactivated and has been evidenced as a putative tumor suppressor in different types of cancer." (PMID 34815381, 2021). "In agreement with our in vitro observations, HACE1 knockdown led to increased levels of HIF1α levels in tumor tissues." (PMID 33603169, 2021). "The results showed that average tumor volumes in the control group increased from 2 to 22 mm3, while increased from 2 to 125 mm3 in the HACE1-overexpression group between pre-radiotherapy and post-radiotherapy." (PMID 34815381, 2021). "A significant correlation was observed between high HIF1α and low HACE1 expression in both tumor cohorts, highlighting the inverse relationship between HACE1 and HIF1α levels in vivo." (PMID 33603169, 2021). "Consistent with our previous findings, HACE1 protein levels were reduced in all tumor cases tested (n = 3) compared to the patient-matched normal kidney, while HIF1α levels were correspondingly increased." (PMID 33603169, 2021).
tumor (continued). "Together, these data provide additional mechanistic insights into the tumor suppressor activity of HACE1, namely through the regulation of HIF1α." (PMID 33603169, 2021). "HACE1 is considered as a tumor suppressor for degradation of Rac1 since HACE1 inhibits reactive oxygen species (ROS) generation by Rac1-dependent NADPH oxidases." (PMID 31248165, 2019). "Immunoblot analysis of tumor lysates with anti-HA antibodies confirmed equal HACE1 expression in HA-HACE1 and HA-HACE1-C876S-expressing tumors." (PMID 30622235, 2019). "Eleven cases (44%) were completely negative for HACE1 staining, while the remaining 14 cases showed variable degrees of HACE1 staining, ranging from positive staining in 5–90% of tumor cells, with a median value of 40%." (PMID 30622235, 2019). "The HACE1 gene, localized to human chromosome 6q21, encodes the HACE1 HECT E3 ligase, a tumor suppressor in diverse tumors that acts in part by targeting the activated form of RAC1 GTPase for proteasomal degradation." (PMID 30622235, 2019). "HACE1 is an important tumor suppressor whose expression is lost in a variety of human cancers, including Wilm’s tumor, B-cell lymphoma, and colorectal, gastric and breast cancers." (PMID 29362425, 2018). "To testify the influence of HACE1 on tumor growth, we performed in vivo study by injecting SGC7901 cells subcutaneously into nude mice." (PMID 29673126, 2018). "Studies, in vivo and in vitro, showed that overexpressing HACE1 inhibited tumor proliferation and migration, and enhanced cell apoptosis." (PMID 29673126, 2018). "Intriguingly, the aberrant low expression of HACE1 notably correlated to a poor pathological differentiation of tumor." (PMID 29673126, 2018). "We have previously demonstrated that ubiquitylation of OPTN by tumor-suppressing E3 ubiquitin ligase, HACE1, promotes the formation of autophagy receptor complex and activates autophagy." (PMID 30519240, 2018). "The significance of Rac1 ubiquitylation was revealed by the discovery of HACE1 ubiquitin ligase as a tumor suppressor." (PMID 30544910, 2018). "The E3 ubiquitin ligase HACE1 is a potent tumor suppressor that controls cell proliferation and ubiquitylates the small GTPase Rac1 to target it to proteasomal degradation." (PMID 28317937, 2017). "It has been shown that HACE1 expression is reduced in multiple human tumors, and forced expression of HACE1 in human tumor cell lines inhibits cell growth in vitro and in vivo." (PMID 27653971, 2016). "Re-expression of HACE1 in human tumor cells directly abrogates in vitro and in vivo tumor growth, which is dependent on its E3 ligase activity." (PMID 27213432, 2016). "Since our tumor model of HER2 overexpression and HACE1 loss is driven by Rac1 hyperactivation, we evaluated the antitumor activity of EHT1864 in orthotopic-implanted MCF12A-HER2 shHACE1 cells." (PMID 25659579, 2015). "Although the knockdown of HACE1 or overexpression of HER2 alone in HMECs is not sufficient for tumorigenesis, HER2 overexpression combined with HACE1 downregulation fully transforms HMECs resulting in robust tumor formation." (PMID 25659579, 2015). "In common with other cancers, WTs also show tumour suppressor gene silencing which includes genes such as HACE1 (73% of tumours analysed), RASSF1 (56%), CASP8 (43%), MGMT (30%), RASSF5/NORE1 (15%), and CDKN2A (10–15%)." (PMID 19956686, 2009). "HACE1 is an important tumor suppressor that is depleted in many malignant tumors." (PMID 40948788, 2025). "The current study indicates that the tumor suppressor function of HACE1 may be closely related to its anti-oxidative stress capacity and autophagic activity." (PMID 40948788, 2025). "Notably, the HACE1+siTRIP12 group exhibited significantly enhanced tumor growth compared to the HACE1 group." (PMID 38706891, 2024). "Extensive evidence underscores HACE1's role as a tumor suppressor in various human cancers." (PMID 38706891, 2024).
tumor (continued). "Due to the fact that HACE1 is misregulated in many cancers, our findings could pave the way for the development of therapeutic drugs that could modulate HACE1 dimerization to restore its tumor suppressor function." (PMID 37537642, 2023). "In fact, HACE1 is considered to act as a tumour suppressor whose downregulation could enhance tumour growth and progression, whereas its overexpression could inhibit tumour development." (PMID 35678127, 2022). "HACE1 was discovered as a chromosome 6q21 tumor-suppressor gene in Wilms’ tumors." (PMID 34199773, 2021). "Subsequently, HACE1 is noted as a tumor suppressor in multiple cancers." (PMID 34199773, 2021). "In addition to WT, HACE1 inactivation has been reported in multiple other tumor types, including non-Hodgkin’s lymphoma, as well as lung, ovarian, pancreatic, and prostate carcinomas." (PMID 33603169, 2021). "To better understand the regulatory mechanisms that underpin stress adaptation in cancer cells, we examined how the previously identified tumor suppressor HACE1 might function in such adaptive processes, given its previous links to cell stress." (PMID 33603169, 2021). "However, the direct regulatory pathways whereby HACE1 confers this tumor-suppressive effect remain to be fully elucidated." (PMID 33603169, 2021). "HACE1 immunoreactivity was estimated by counting the number of positive cells per 1000 tumor cells." (PMID 30622235, 2019). "Furthermore, a direct interaction between the two SLRs has been demonstrated in a study showing that tumor-suppressor HACE1, a ubiquitin ligase, ubiquitinates OPTN and promotes its interaction with p62 to form the autophagy receptor complex." (PMID 30818338, 2019). "However, in the remaining cases, protein expression was observed in 5–90% of cells, and reduced HACE1 expression (i.e. immunostaining in <40% of cells) significantly correlated with higher tumor grade." (PMID 30622235, 2019). "The most studied function of HACE1 is its involvement in tumor development." (PMID 27213432, 2016). "HACE1 gene is located on chromosome 6q21, a prominent tumor-suppressor region." (PMID 27213432, 2016). "The tumor suppressive function of HACE1 is also characterized." (PMID 27213432, 2016). "HACE1 has been characterized as an important tumor suppressor." (PMID 27213432, 2016). "HACE1 loss coupled with the overexpression of a Rac1 activator such as HER2 results in hyperactivation of Rac signaling and is sufficient to transform normal mammary epithelial cells allowing tumor formation in mice." (PMID 25659579, 2015). "To identify genes capable of cooperating with HER2/neu to fully transform mammary epithelial cells, we used an insertional mutagenesis screen on cells isolated from wild-type neu expressing mice and identified the E3 ligase HACE1 as HER2 cooperative tumor suppressor gene." (PMID 25659579, 2015). "We identified HACE1 as a tumor suppressor gene that cooperates with HER2." (PMID 25659579, 2015). "Furthermore, the mutant cell line (three lysine residues mutated to arginine residues, 3KtoR) could reduce ubiquitylation by HACE1 and translocation to mitochondria, and alleviate cisplatin stress on tumour cells compared with wild‐type cells." (PMID 35475325, 2022). "However, the association of HACE1 with cancer is not new, since promoter hypermethylation of HACE1 gene and reduced protein expression have been observed in several tumour types." (PMID 35678127, 2022). "Therefore, HACE1 is considered to be a tumor suppressor gene." (PMID 27653971, 2016). "More and more studies show that that HACE1 activates selective autophagy mediated by the HACE1-OPTN-P62 axis through ubiquitination of OPTN, thereby inhibiting tumor cell growth and progression." (PMID 40948788, 2025). "In concordance, HACE1 suppressed the expression of CCND1, Bcl-2, and MMP2 in tumor tissue, with EHop-016 intensifying the inhibitory effects on these proteins." (PMID 38706891, 2024).
tumor (continued). "Animal experiments concurred, displaying that TRIP12 silencing mitigated HACE1's inhibitory impact on tumor growth and RAC1 protein levels in tumor tissue." (PMID 38706891, 2024). "Most importantly, TRIP12 inhibition blocked HACE1-driven RAC1 ubiquitination and mitigated the inhibitory effects of HACE1 on ESCA cells, alleviating tumor growth in the tumor-bearing nude mouse model." (PMID 38706891, 2024). "For in vivo studies, we used Eca-109 cells in three groups: NC, HACE1, and HACE1+siTRIP12, and observed that TRIP12 silencing significantly exacerbated tumor growth on the basis of HACE1 overexpression." (PMID 38706891, 2024). "Intriguingly, TRIP12 inhibition blocked HACE1-driven RAC1 ubiquitination and mitigated the inhibitory effects of HACE1 on ESCA cells, alleviating tumor growth in the tumor-bearing nude mouse model." (PMID 38706891, 2024). "To ascertain the in vivo implications of HACE1 inhibition of ESCA and the potential involvement of RAC1, we conducted tumor-bearing nude mouse experiments, employing a RAC1 inhibitor to block the RAC1 pathway." (PMID 38706891, 2024). "HACE1 overexpression inhibited the malignant biological behavior of ESCA cells, leading to restrained tumor growth in mice." (PMID 38706891, 2024). "The HACE1 (HECT domain and ankyrin repeat-containing E3 ubiquitin-protein ligase) gene is a tumor suppressor that inhibits the growth, invasive capacity, and metastasis of cancer cells." (PMID 33603169, 2021). "A protein product of the HACE1 (HECT domain and ankyrin repeat containing E3 ubiquitin protein ligase 1) gene is a potential tumor suppressor and participates in the specific tagging of target proteins that subsequently results in proteasome degradation." (PMID 33552117, 2020). "The HACE1-OPTN axis increases autophagic flux of intracellular autophagy and inhibits proliferation of tumor cell." (PMID 30944378, 2019). "Although several cellular targets of HACE1 have been identified, the control exerted by HACE1 on Rac1 is essential in the regulation of ROS production by NADPH oxidase, cyclin-D1 expression, and the tumor suppressor function of HACE1 (21, 24, –, 26)." (PMID 41051206, 2025). "Silencing OPTN led to the acquisition of enhanced integrin-mediated adhesion and ECM stiffness-independent signaling and proliferation, attributes that may contribute to HACE1- and OPTN-induced tumor suppressor functions." (PMID 36229487, 2022). "We also tested the effects of HACE1 and HACE1C876S on tumor growth in nude mice, and found that xenograft tumors produced by HACE1/HACE1C876S overexpression-U87 cells grew faster and exhibited larger tumor weight than control tumors." (PMID 34815381, 2021). "In line with its putative tumor-suppressive role, the absence of HACE1 correlated with enhanced HIF1α protein levels in WT tissues compared to the patient-matched normal kidneys." (PMID 33603169, 2021). "They showed that although the HACE1 locus was not directly interrupted by the translocation in the index Wilms’ case, its expression was markedly lower in tumor tissues compared with adjacent normal kidney." (PMID 34707697, 2012). "Although knockdown of HACE1 alone was not sufficient for normal mammary epithelial cells to become tumorigenic in mice, HER2 overexpression coupled with knockdown of HACE1 allowed robust tumor formation." (PMID 25659579, 2015).